TET2 (tet methylcytosine dioxygenase 2)
Diseases named in the same sentence as TET2 in open-access papers (continued):
Sharing a sentence is not in itself a finding about the gene and the disease.
Sjögren’s syndrome (1 paper, 2021). "Additionally, immunofluorescence analysis of the levels of Tet2, 5mC, 5hmC and DNMTs showed that, in Sjögren’s syndrome (SS) patients, the levels of both 5mC and DNMTs were decreased, while those of Tet2 and 5hmC were increasingly enriched in salivary gland inflammatory cells." (PMID 34222235, 2021).
Skin tumours (1 paper, 2023). "Skin tumours taken from different anatomical sites at diagnosis contained two distinct malignant clones that arose from a common TET2-mutated precursor in the marrow." (PMID 37286599, 2023). "Only the truncal TET2 and SRSF2 mutations were identified in the matched skin tumour, suggesting derivation from an ancestral clone that diverged before alterations that remained isolated to the marrow." (PMID 37286599, 2023).
small vessel stroke (1 paper, 2025). "It shows that TET2 is associated with small vessel stroke possibly via a pro‐inflammatory pathway." (PMID 40093911, 2025).
synovial sarcoma (1 paper, 2025). "We first investigated whether the genes that regulate DNA methylation (DNMT1, DNMT3A, DNMT3B, TET1, TET2, TET3) are misexpressed, mutated, or amplified in synovial sarcoma." (PMID 40299558, 2025).
systemic sclerosis (1 paper, 2021). A chronic disorder, possibly autoimmune, marked by excessive production of collagen which results in hardening and thickening of body tissues. "In peripheral blood mononuclear cells, TET2 gene expression was decreased by 86% in systemic sclerosis (SSc)-PAH patients and decreased by 86.7% in iPAH patients compared relatively to healthy controls." (PMID 33805595, 2021).
Thromboembolism (1 paper, 2025). The formation of a blood clot inside a blood vessel that subsequently travels through the blood stream from the site where it formed to another location in the body, generally leading to vascular occlusion at the distant site. "While some papers propose that TET2 has an antithrombotic effect, others point to a prothrombotic effect or a more subtle effect of TET2 on the development of thromboembolism." (PMID 41169875, 2025).
tuberculosis (1 paper, 2024). A chronic, recurrent infection caused by the bacterium Mycobacterium tuberculosis. "In addition, the TET2 gene also affects the host’s resistance to tuberculosis, the specific mechanism being that the binding of Tet2 to NF-κB induces the demethylation of TNF, where NF-κB is an important factor affecting the phenotypes of cell proliferation, apoptosis and inflammation." (PMID 38200892, 2024).
venous thromboembolism (1 paper, 2025). Occlusion of the lumen of a vein by a thrombus that has migrated from a distal site via the blood stream. "In conclusion, the important role of TET2 in venous thromboembolism (VTE) marks it as a key focus of haematological and vascular biology research." (PMID 41169875, 2025). "However, the exact function of TET2 in hematopoietic processes and, therefore, possible involvement in venous thromboembolism (VTE), especially in malignancies, remains an active area of research." (PMID 41169875, 2025). "However, there is no review on the mechanism and clinical significance of TET2 in venous thromboembolism." (PMID 41169875, 2025).
tumor (400 papers, 2010 to 2026). "Immunohistochemistry revealed a markedly elevated Ki-67 proliferative index (> 90%), and genomic profiling identified pathogenic EZH2 and TET2 mutations with a high tumor mutational burden." (PMID 42088612, 2026). "Distinct from our previous study on TET2 nuclear loss, which can be observed in the whole tumor progression process, the nuclear increase of TET2 was only observed in tumors at the beginning of metastasis." (PMID 41605908, 2026). "Although many TET2 mutations are recurrent across a range of malignancies, there are a number of mutations that appear to be tumor‐specific." (PMID 40116537, 2025). "TET2 mutations had the largest relative tumor-infiltrating clone size compared to other CHIP gene mutations (median tumor over blood VAF ratio of 0.18 versus 0.13, p<0.001)." (PMID 40267425, 2025). "Emerging evidence demonstrates that AID engages in multifaceted transcriptional regulation through collaborative interactions with epigenetic modifiers such as DNMT1 and TET2, particularly modulating tumor-associated gene networks." (PMID 40270606, 2025). "In a subset of AITLs, TET2 or DNMT3A have higher‐than‐expected VAF relative to other mutations or tumor content and are possible founder mutations present in hematopoietic stem/progenitor (HSPC) cells." (PMID 40510016, 2025). "For example, TET2 deficiency in immune cells has been shown to exacerbate tumour progression by increasing angiogenesis in lung cancer models." (PMID 41169875, 2025). "The same TET2 mutation was also detected in bystander B cells of AITL patients as in AITL tumor T cells, suggesting a possible shared clonal origin or cross-lineage evolution." (PMID 41357603, 2025). "Overall, mutated genes identified in the tumor‐enriched cohort were concordant, with recurrent variants identified in TET2, DNMT3A, RHOA, IDH2, and TET3." (PMID 40510016, 2025). "Although the evolution of neoplastic T-cell-specific mutations varied depending on the model, expansion of TET2-mutated cells was found in every tumor bearing a TET2 mutation (TFHL and CU-TFHL)." (PMID 40394210, 2025). "Concerning the effects of hematopoietic Tet2 loss of function in tumor progression the reports are mixed." (PMID 40517440, 2025). "In these hematologic malignancies, mutations in TET2, a tumor suppressor, drive tumorigenesis and development; however, insufficient mutations in a single gene cause the transformation of hematologic malignancies." (PMID 40599235, 2025). "For example, TET2 mutations or downregulation can promote the maintenance of cancer stemness and tumor immune evasion in lung cancer cells." (PMID 41394878, 2025). "The DNA demethylase TET2 was shown to interact with AR to regulate the expression of tumor-suppressor genes, suggesting that it has a role in tumor suppression and its loss can lead to the progression of PCa." (PMID 40833121, 2025). "For instance, restoration of TET2 function in TET2-deficient cancer cells is associated with reduced tumour growth and enhanced sensitivity to chemotherapeutic agents." (PMID 41169875, 2025). "Consistent with published evidence that TET2 mutations can functionally remodel myeloid responses,39TET2-mutant myeloid cells displayed enhanced protumorigenic capacity in tumor organoid co-cultures compared to wild-type myeloid cells." (PMID 40267425, 2025). "Mutations in DNMT3A and TET2 were detected in the majority of patients with AITL in both pre-treatment tumours (8/12 and 11/12, respectively) and in ctDNA where available (5/6 and 6/6, respectively)." (PMID 40724970, 2025). "The loss of function TET2 gene allows a switch of immunosuppressive tumor-associated macrophages to proinflammatory ones." (PMID 39456832, 2024). "Loss of TET2 in tumor-associated macrophages results in increased expression of inflammatory cytokines." (PMID 39659792, 2024).
tumor (continued). "Quantifying intercellular signaling from the scRNA-seq dataset showed that T cell–derived IFN-γ–induced signaling within the tumor and tumor microenvironment requires tumor-associated TET2 expression, which is enhanced by VC treatment." (PMID 39388288, 2024). "TET2 upregulation and tumor suppressor re-expression were associated with resistance conferred by DNMT1 deletion." (PMID 39057134, 2024). "While TET1 demonstrates only limited correlation with tumor staging, TET2 exhibits significant associations in STAD, LIHC, and LUAD (p < 0.01)." (PMID 39104395, 2024). "Tumor-associated TET2 activity drives antigen presentation and promotes tumor-associated T cell activity, which is enhanced by vitamin C therapy." (PMID 39388288, 2024). "A loss-of-function TET2 mutation in tumor infiltrating myeloid cells was shown to increase angiogenesis in a lung cancer animal model, exacerbating tumor progression." (PMID 39172974, 2024). "We showed previously that vitamin C (VC), a cofactor of TET2, enhances tumor-associated T cell recruitment and checkpoint inhibitor therapy responses in a TET2-dependent manner." (PMID 39388288, 2024). "Meanwhile the previous study has suggested a tumor suppressive role in a Tet2-deficient pre-leukemic context." (PMID 38609495, 2024). "Tumor-associated roles for TET2 in enhancing T cell responses presumably include antigen presentation as well as other mechanisms such as production of key chemokines." (PMID 39388288, 2024). "Loss of TET2 expression in the B16 tumor model led to reduced T cell recruitment, while stimulation of tumors with VC promoted T cell recruitment and enhanced response to checkpoint inhibitor therapy." (PMID 39388288, 2024). "In contrast, EBV-positive nodal T-cell and NK-cell lymphoma is a nodal neoplasm mainly diagnosed in Asian patients and often shows mutations in TET2, PIK3CD, DDX3X and STAT3." (PMID 38835967, 2024). "Our results demonstrate the importance of tumor-associated TET2 activity as a critical mediator of tumor immunity, which is augmented by high-dose VC therapy." (PMID 39388288, 2024). "While TET2 loss serves as a risk factor for further malignant degeneration, TET2 mutations alone are insufficient to trigger neoplasia." (PMID 36639817, 2023). "It is now known that AITL, CMML and AITL-derived DLBCL are neoplasms that share common age-related ancestral mutations (TET-2 and DNMT3A)." (PMID 37182145, 2023). "TET2 functions as a tumor suppressor and thus loss-of-function mutations are found in myeloid malignancies." (PMID 37937078, 2023). "TET2 is a tumor suppressor and loss-of-function mutations of TET2 frequently happen in hematopoietic malignancy." (PMID 37550284, 2023). "TET2 acts as a tumor suppressor, which is mutated or inactivated in various types of tumors, while the physiological roles of TET2 in normal cells still remain elusive." (PMID 37550284, 2023). "For example, Tet2 deletion in mouse melanoma and colon tumor cells was associated with decrease in chemokine expression and tumor-infiltrating lymphocytes." (PMID 36672677, 2023). "Prior studies using single-cell sorting of neoplastic T cells and myeloid cells have demonstrated common shared TET2 mutations as well as different mutations in each tumor, confirming clonal relatedness." (PMID 38199781, 2023). "We found that loss of TET2 indeed leads to increased mRNA stability of urea cycle enzymes in tumor cells and mouse primary liver and lung cells when the de novo transcription has been blocked." (PMID 37550284, 2023). "The tumor demonstrated monoclonal TR gene rearrangement and mutations of TET2 and DNMT3A, which are uncommon in ENKTL." (PMID 37646869, 2023). "Tet2 gene is a tumor-suppressor gene, and Tet2 gene mutation is one of the factors that can trigger AML and CML." (PMID 38075916, 2023). "And it is notable that Tet2 knockout in Ctbp2-cKO mice can compensate for Ctbp2 loss in terms of tumor progression." (PMID 37643007, 2023).
tumor (continued). "Subsequent analysis revealed clonal expansion of TET2-deficient germinal center B cells in the tumor-bearing mice, unique mutations in core histones developed in murine clonal B cells and that inhibition of CD40-CD40L interactions prolonged survival in mice." (PMID 37841428, 2023). "The presence of TET2-mutated immune cells in AITL patients led to the question if TET2 mutations alter tumor immunity to promote T cell lymphomagenesis." (PMID 37841428, 2023). "In particular, the tumour suppressor TET2 is implicated in haematological malignancies and 134 TET2 unique variants were reported, none of which were seen in external databases." (PMID 35346197, 2022). "We found that TET2, which was highly expressed in adjacent normal tissues compared to tumor tissues, was closely associated with many infiltrating immune cells." (PMID 35603206, 2022). "We next used data generated by TCGA12 to investigate DNAm profiles in tumor samples from AML patients harboring either DNMT3A or TET2 driver mutations." (PMID 36097025, 2022). "TET2, one of the most frequently mutated genes in diffuse large B-cell lymphoma, works as a tumor-suppressor gene." (PMID 36685517, 2022). "According to recent studies, TET2 has been closely associated with solid tumors, and plays an important role in tumor occurrence and development." (PMID 35223782, 2022). "Genomic profiling of AITL, DLBCL, and MDS samples revealed that the tumor cells from all samples shared common mutations in TET2 and DNMT3A." (PMID 35846192, 2022). "Recently, TET2 mutations have been detected in the AITL tumor clones of bystander B cells in AITL samples." (PMID 36428791, 2022). "This phenomenon is in accordance with previous reports that TET2 mutations alone often require other gene mutations as a secondary hit to induce the occurrence and development of tumours." (PMID 35279121, 2022). "TET2 deficiency in tumor-associated macrophages results in defective immunosuppressive capacity and an altered cytokine expression profile." (PMID 36685517, 2022). "A significant association was observed between TET2 expression and the tumor stage in OV in TCGA database." (PMID 35223782, 2022). "TET2 expression was significantly positively correlated with immune-infiltrating tumor-associated fibroblasts in BRCA, CESC, and OV." (PMID 35223782, 2022). "This is similar to a study showing that, in the tumor niche, TET2-deficient TAMs select for a proinflammatory signature and prevents the alternative/immunosuppressive phenotype of macrophages that supports tumor growth." (PMID 35393954, 2022). "The tumor suppressor gene Tet Methylcytosine Dioxygenase 2 (TET2) encodes for an α-ketoglutarate and iron-dependent dioxygenase that has a critical role in 5-hydroxymethyl cytosine formation via the oxidation of 5 methylcytosine (5mC)." (PMID 35625998, 2022). "These inactivating TET2 mutations suggest a tumor suppressive role for the TET2 protein, which is confirmed by the spontaneous development of myeloid, T-cell, and B-cell malignancies in a TET2 KO mouse model." (PMID 36059621, 2022). "Elevated LDH levels and positive B symptoms are considered indicators of tumor load and play an overwhelming role in tumor maintenance, thereby suggesting that TET2 mutations can lead to increased tumor burden." (PMID 36428791, 2022). "In most cases, RHOA mutations are specifically identified only in tumor cells, whereas TET2 mutations are found in both tumor and non-tumor hematopoietic cells." (PMID 36428791, 2022). "In KDM2A-deficient cells, TET2 upregulation can induce the reactivation of two tumor-suppressive genes, epithelial cell adhesion molecule and e-cadherin located downstream of TET, and thus inhibiting cell migration and invasion." (PMID 35223782, 2022).
tumor (continued). "These investigators described a disrupted IFNγ-JAK-STAT signaling cascade in Tet2-deficient tumor cells that we also found with β cells." (PMID 34417463, 2021). "MiR‐22 has also been found to target many genes encoding cancer‐associated proteins, including the TET2 tumor suppressor, HDAC6, ERBB3, CDC25C, EVI‐1, and P21, which play different roles in different types of cancer." (PMID 33159388, 2021). "Here, we identified a tumor suppressor role of the acetyltransferase p300 in clinically relevant MDS models driven by mutations in the epigenetic regulators TET2, ASXL1, and SRSF2." (PMID 34622806, 2021). "Mutations in the widely recognised tumour suppressive TET2 gene have been shown to be sufficient to instigate myeloid malignancies in mice." (PMID 34065087, 2021). "Previous studies of Tet2-deficient tumor cells identified impaired STAT1 signaling that prevented the expression of chemokines and PD-L1 expression and enabled tumors to evade anti-PD-L1 immune therapy." (PMID 34417463, 2021). "These together suggest that the loss of TET2 promotes the accessibility of ETS enriched gene loci which mediate the enhanced anti-tumor function." (PMID 35087832, 2021). "Both of these genes are tumor suppressors in human DLBCLs, and Tet2 loss of function was also shown to induce lymphomagenesis in IuBcl6 mice." (PMID 34621263, 2021). "As a tumor suppressor, loss of function of TET2 caused by mutation or deletion has previously been reported in several types of cancer." (PMID 33097695, 2020). "Such TET2 loss-of-function mutations are associated with a DNA hypermethylation phenotype, tumour progression, and poor patient outcome." (PMID 31963585, 2020). "Research on Tet2 loss in immune-cell responses and tumor development unveils the significance of DNA methylation in various biological activities, and in the advancement of hematological malignancies and solid tumors." (PMID 33184433, 2020). "According to the determined allele frequencies, the TET2 mutation was linked to the chromosome harboring the C allele of rs1008658 and was lost in the tumor cells." (PMID 33246418, 2020). "TET2 (WT) cells caused smaller tumor masses than the mock vector control after 6 weeks of observation (SMMC-7721/FGFR3∆7–9/TET2 (WT), 562.8 ± 332.15 mm3; SMMC-7721/FGFR3∆7–9/vector, 1604.6 ± 500.2 mm3; P < 0.05)." (PMID 33097695, 2020). "The epigenetic changes induced by TET2 mutations offer a rationale for using demethylating agents in TET2-mutated neoplasms." (PMID 33160401, 2020). "Methylation appeared to be dysregulated in CPM with a bias towards a hypermethylator phenotype caused by somatic mutation of the TET2 tumour suppressor and CDH7 chromatin regulator." (PMID 33144643, 2020). "CPM were characterised by frequent Wnt/ β catenin negative regulator mutations, TET2 mutations, mismatch repair mutations and high tumour mutational burden." (PMID 33144643, 2020). "Methylation of ETNK2, NTN1, and NUDT10 was increased in ERG-fusion negative tumors, which is concordant with the significant loss of TET2 expression in these tumor samples." (PMID 30917865, 2019). "In this cell line TET2 acts as an oncogene while in other AML cases TET2 is mutated and performs tumor suppressor activity." (PMID 31825998, 2019). "There is clear evidence for genetic intra-tumor heterogeneity in human PTCL: TET2 is mutated in a greater proportion of cases than RHOA and inspection of the published VAF results suggests sub-clonal variation in some cases." (PMID 31013298, 2019). "In a wide variety of human cancers, reduced expression of TET1 and TET2 proteins and loss of 5hmC has been documented, and the tumor suppressive role of TET proteins is extensively associated with the prevention of tumorigenesis." (PMID 30045709, 2018). "One possibility is that the G17V RHOA mutation occurs in TET2-mutated premalignant cells and facilitates the selective differentiation of TET2-mutated premalignant cells into tumor cells with the TFH phenotype." (PMID 28157189, 2017).